MAMDC4 (MAM domain containing 4)
Description:
Probably involved in the sorting and selective transport of receptors and ligands across polarized epithelia.
Synonyms: AEGP; DKFZp434M1411; EDTB
Tractability: Antibody: UniProt predicts a signal peptide or a membrane-spanning region.
Gene: Protein-coding gene on chromosome 9 (136,850,943 to 136,860,802, forward strand). Ensembl gene ENSG00000177943.
Subcellular location: Membrane
Subcellular location (Human Protein Atlas): Nucleoplasm; Cytosol
Gene Ontology:
Biological process: nervous system development
Cellular component: membrane
Genetic constraint (gnomAD): Loss-of-function variants: 168 observed, 143.69 expected, observed/expected ratio (o/e) 1.17, 90% interval 1.03 to 1.33. The synonymous counts are far from expectation, so gnomAD's model fits this gene poorly and the ratio says little. Missense variants: 1,701 observed, 1,499.4 expected, observed/expected ratio (o/e) 1.13, 90% interval 1.09 to 1.18. Synonymous variants: 744 observed, 634.49 expected, observed/expected ratio (o/e) 1.17, 90% interval 1.1 to 1.25.
Homologues: Orthologues: chimpanzee MAMDC4 (99% identical), pig MAMDC4 (76% identical), mouse Mamdc4 (73% identical), tropical clawed frog mamdc4 (36% identical), zebrafish mamdc2b (17% identical). Paralogues in human: MALRD1 (27% identical), MAMDC2 (16% identical), MDGA1 (12% identical), MDGA2 (12% identical).
Diseases named in the same sentence as MAMDC4 in open-access papers:
MAMDC4 is named in the same sentence as 8 diseases in open-access papers, as found by Europe PMC text mining. Sharing a sentence is not in itself a finding about the gene and the disease. The quoted sentences say what the papers report.
steatosis (2 papers, 2021 to 2024). Increased lipid within the cytoplasm of cells. "Eventually, we determined 10 hub genes (Down-regulated genes: MYC, TGFB3, ADAMTS1, THBS1, RASD1, PCDH20; Up-regulated genes: MAMDC4, CYP7A1, GINS2, and PDLIM3) related to NAS and steatosis." (PMID 34777484, 2021). "In a protein–protein interaction network, IGSF9 was found to have a central position, being correlated to FGF21, CES1, MAMDC4, and afamin (AFM) in PLHIV with steatosis, and to AFM and GHR in those without steatosis." (PMID 39426127, 2024).
colon cancer (1 paper, 2024). "To test if expression of MAMDC4 impacts proliferation in intestinal epithelial cells in vitro, we utilized the colon cancer Caco2BBE cell line." (PMID 38787854, 2024).
diabetes (1 paper, 2016). "Expression of other coding genes regulated by diabetes with FC > =(+/-) 1.5 and completely reversed by P78 include Mamdc4, Kdm4b, Tmem252, Selm, and Hpd." (PMID 27855634, 2016). "Treatment also completely reversed diabetes-induced expression changes of Mamdc4, Kdm4b, Tmem252, Selm, and Hpd while others were returned in the direction of normal levels from their diabetes-induced state by ~50%." (PMID 27855634, 2016). "Ugt1a and Mamdc4, which were downregulated and Cyp4a14 and Kdm4b, which were upregulated in diabetes by 2-4 fold also had near complete restoration of expression levels to control by P78." (PMID 27855634, 2016).
Type 2 diabetes (1 paper, 2016). "Ugt1a genetic variants predict high risk for Type 2 diabetes mortality while Mamdc4 deletions are associated with a group of inflammatory axial diseases." (PMID 27855634, 2016).
cancer (2 papers, 2021 to 2023). A tumor composed of atypical neoplastic, often pleomorphic cells that invade other tissues. "The remaining genes in the hyperloss category are ECHDC3, KRTCAP3, LURAP1, and MAMDC4, none of which are known drivers in cancer." (PMID 37245006, 2023).
tumor (2 papers, 2021). "We found that CYP7A1, GINS2, and PDLIM3 were significantly up-regulated, and MYC, MAMDC4, ADAMTS1, THBS1, and RASD1 were significantly down-regulated in HCC tumor samples compared with normal samples using the TCGA dataset." (PMID 34777484, 2021). "We found that CYP7A1, GINS2, and PDLIM3 were significantly up-regulated, and MYC, MAMDC4, ADAMTS1, THBS1, and RASD1 were significantly down-regulated in HCC tumor samples compared to normal samples." (PMID 34777484, 2021).
MAMDC4 also shares sentences with these, for which no sentence is quoted: liver cancer (1 paper); prostate carcinoma (1).